TMED3 (transmembrane p24 trafficking protein 3)
Diseases named in the same sentence as TMED3 in open-access papers (continued):
Sharing a sentence is not in itself a finding about the gene and the disease.
malignant melanoma (2 papers, 2023 to 2025). "Having shown that TMED3 inhibition displayed potent anti-melanoma in vitro and in vivo, we further investigated the underlying mechanism of TMED3’s action in melanoma." (PMID 36991473, 2023). "More importantly, we demonstrated that TMED3 promotes melanoma cell proliferation and migration through a mechanism that targets CDCA8 and involves the PI3K/AKT signaling pathway." (PMID 36991473, 2023). "From this, we inferred that TMED3 promotes the proliferation and migration of melanoma cells via targeting CDCA8." (PMID 36991473, 2023). "We next detected TMED3 mRNA levels in a panel of melanoma cell lines." (PMID 36991473, 2023). "To clarify the underlying roles of TMED3 in MM progression, we performed IHC analysis on a tissue microarray containing 167 melanoma specimens and 30 non-tumor samples." (PMID 36991473, 2023). "Additionally, silencing TMED3 suppressed cell proliferation and tumor growth in melanoma cell and animal models." (PMID 36991473, 2023). "As expected, all melanoma cells harbored high TMED3 mRNA levels." (PMID 36991473, 2023). "In this section, we wondered whether TMED3 depletion could influence melanoma tumor outgrowth." (PMID 36991473, 2023). "However, evidence describing TMED3 in the context of malignant melanoma (MM) is scarce." (PMID 36991473, 2023). "The results suggested that TMED3 protein expression was significantly upregulated in 52.1% of melanoma specimens (87/167), while the majority of 30 non-tumor samples exhibited low TMED3 levels (29/30)." (PMID 36991473, 2023).
prostate tumor (2 papers, 2012 to 2025). "Since ERGIC1 and TMED3 expression correlated with ERG expression levels in ERG positive primary prostate tumors, the potential effect of their expression on ERG mRNA expression was studied in VCaP cell line." (PMID 22761906, 2012). "TMED3 downregulation greatly inhibited prostate tumor growth in the mice." (PMID 39735675, 2025).
bladder cancer (1 paper, 2021). "While CNN3, SHISA2, TMED3, SRGN were downregulated in persistently infected bladder cancer cells." (PMID 34044804, 2021).
breast tumor (1 paper, 2021). "Furthermore, it negatively regulates TMED3 to inhibit the proliferation, migration and invasion of breast tumor." (PMID 33902604, 2021).
colon adenocarcinoma (1 paper, 2014). "Data mining from public platforms revealed that the mRNA levels of TMED3, but not of SOX12, increased in colon adenocarcinoma versus matched normal colon tissue." (PMID 24920608, 2014).
metastatic tumors (1 paper, 2025). "After confirming the regulatory role of TMED3 on ZBTB7A in vitro, we further validated ZBTB7A expression in clinical specimens and metastatic tumors through hematoxylin and eosin (H&E) staining and immunofluorescence." (PMID 40471367, 2025).
oral cancer (1 paper, 2023). "Another novel oral cancer susceptibility locus is in the TMED3 gene on 15q25.1." (PMID 36769103, 2023).
tumor (19 papers, 2014 to 2025). "For instance, elevated TMED3 expression in osteosarcoma and breast cancer is closely linked to enhanced tumor invasiveness and a worse prognosis." (PMID 40471367, 2025). "After 23 days of monitoring, downregulation of TMED3 was found to cause the tumor in mice to be weaker than that of the control group in terms of volume and weight." (PMID 34838013, 2021). "Thus, we subcutaneously injected TMED3-deficient A375 cells into nude mice, and measured tumor growth indicators." (PMID 36991473, 2023). "In some tumors, abnormal expression of TMED3 promotes tumor cell growth, migration, and invasion by regulating key signaling axes such as Wnt/β-catenin and ERK/MAPK." (PMID 40471367, 2025). "TMED3 protein levels in the tumor tissues decreased significantly after shTMED3 administration in vivo." (PMID 39735675, 2025). "In vivo experiments, using TMED3-KD lentivirus-transfected nude mice showed a significant reduction in tumor fluorescence intensity and volume compared to controls." (PMID 40471367, 2025). "Conversely, AKT inhibition reduces TMED3's ability to promote tumor cell proliferation, suggesting that TMED3 functions through the AKT signaling axis." (PMID 40471367, 2025). "While the precise role of TMED3 in different cancers is not fully understood, its complex involvement in tumor progression makes it an important target for studying tumor mechanisms and potential therapeutic strategies." (PMID 40471367, 2025). "The results revealed a significant difference in TMED3 expression between normal and tumor tissues, suggesting a potential correlation between TMED3 expression and these clinical samples." (PMID 40471367, 2025). "In summary, our results confirm that TMED3 is highly expressed in GBM, and its high expression is associated with higher tumor grade and poor prognosis." (PMID 40471367, 2025). "After identifying the potential role of TMED3 in GBM development, we conducted TMED3 knockdown experiments to further investigate its effects on tumor proliferation and invasion." (PMID 40471367, 2025). "TMED3 suppresses distant colon cancer metastases, but promotes tumor progression in liver cancer and breast cancer." (PMID 36991473, 2023). "This analysis confirmed substantially elevated expression levels of TMED3 in tumor tissues relative to normal tissues, particularly in the VCaP and LNCaP cell lines." (PMID 37925432, 2023). "In this study, we characterized the functional significance of TMED3 in MM and identified TMED3 as a tumor-promoting factor in MM development." (PMID 36991473, 2023). "In conclusion, our study identified TMED3 as a tumor promoter in MM, which was upregulated in MM, thereby promoting MM by regulating cell proliferation, apoptosis and cell migration." (PMID 36991473, 2023). "A previous study showed that the expression of TMED3 in tumor cells promotes the progression and development of LUSC." (PMID 37280525, 2023). "More strikingly, depletion of TMED3 evidently arrested tumor growth, mainly resulting in a restraint of tumor volume and weight." (PMID 36991473, 2023). "The following in-vivo experiments also verified that tumor growth was inhibited after TMED3 knockdown." (PMID 35854294, 2022). "We suggested that TMED3 functioned as a tumor promoter and played an important role in EC progression via regulating PI3K/AKT signaling pathway." (PMID 35854294, 2022). "According to the bioinformatic analysis derived from TCGA database, the mRNA level of TMED3 were considerably higher in EC tumor tissues than that in normal endometrium tissues (P < 0.001)." (PMID 35854294, 2022). "As a result, we suggested that TMED3 mediated cell phenotype and functioned as a tumor promoter in EC cells via targeting PI3K/AKT signaling pathway." (PMID 35854294, 2022).
tumor (continued). "We firstly investigated the expression of TMED3 using bioinformatic analysis and clinical tissue microarray, then tested cell proliferation, migration and apoptosis after establishing TMED3-knockdown cell models, as well as tumor growth in vivo." (PMID 35854294, 2022). "This study suggested that knocking down TMED3 affected the malignant phenotype of EC cells and thus limited tumor progression, which provided insights to the development of targeted drugs for EC treatment." (PMID 35854294, 2022). "Evidence from in vitro and in vivo experiments demonstrated the tumor-promoting effects of TMED3 in EC development." (PMID 35854294, 2022). "The following Spearman correlation test also indicated that lymphatic metastasis of the tumor was positively correlated with the expression pattern of TMED3 (rs = 0.385, P = 0.035, N = 30), which was also verified through IHC." (PMID 35854294, 2022). "TMED3 knockdown also inhibited osteosarcoma cell proliferation and tumor growth by inhibiting RPS15A." (PMID 35854294, 2022). "For example, TMED3 inhibits the distant metastasis of colon cancer, but promotes tumor progression of liver cancer and breast cancer." (PMID 34429402, 2021). "Expression profiles were analyzed based on 501 tumor samples and 49 normal samples in the TCGA (The Cancer Genome Atlas) database, finding that the expression level of TMED3 in tumor was significantly higher than that in normal (P < 0.01)." (PMID 34429402, 2021). "Consistently, results of western blot indicated that protein expression of TMED3 was highly expressed in tumor tissue." (PMID 34429402, 2021). "As a divergent member of the transmembrane trafficking protein family, TMED3 can promote signal transduction and regulate a variety of tumor cells progression." (PMID 34838013, 2021). "To clarify the underlying role of TMED3 in HCC progression, we performed qRT-PCR analysis of 60 HCC specimens and paired non-tumor (NT) samples." (PMID 27901021, 2016). "High TMED3 expression was associated with positive alpha-fetoprotein (AFP; P = 0.020), larger tumor size (≥5 cm; P = 0.045) and vascular invasion (P < 0.001)." (PMID 27901021, 2016). "Additional in vivo tests supported the finding that TMED3 knockdown inhibits tumor growth." (PMID 37928880, 2023). "In vitro tests revealed that TMED3 inhibition has anti-tumor effects in naked mice." (PMID 37928880, 2023). "The malignant phenotype of EC cells may be impacted by TMED3 knockdown, which could slow tumor growth and provide information for the creation of targeted drugs for the treatment of EC63." (PMID 37928880, 2023). "Specifically speaking, TMED3 siRNA enabled tumor cells to increase cisplatin sensitivity." (PMID 35854294, 2022). "Especially, the expression of TMED3 in tumor grade III was higher than that in tumor grade II." (PMID 34429402, 2021). "TMED2 and TMED3 were respectively reported to be a tumor suppressor and an oncogene in HCC." (PMID 33888099, 2021). "The influence of TMED3 knockdown on tumor growth in vivo was evaluated by mice xenograft models." (PMID 34429402, 2021). "In addition, the tumor contrast photos more intuitively showed that the downregulation of TMED3 weakens the tumor growth in mice." (PMID 34838013, 2021). "In addition, in vivo mice xenograft model further illustrated the inhibition of LUSC tumor growth by TMED3 knockdown." (PMID 34429402, 2021). "However, in other cases, TMED3 may exhibit a protective effect by regulating epithelial-mesenchymal transition or cell adhesion molecules to inhibit the spread of tumor cells." (PMID 40471367, 2025). "Therefore, we identified TMED3 as a tumor promotor in MM, which may be a promising therapeutic target for MM." (PMID 36991473, 2023). "Collectively, these data suggested that TMED3 might be a tumor promotor in MM outgrowth." (PMID 36991473, 2023).
tumor (continued). "We next detected whether TMED3 was significantly expressed based on the characteristics of patients or tumors, i.e., patient’s age, tumor size, tumor grade, the extent of tumor infiltration, tumor pathological stage, whether lymphatic metastasis occurred and whether tumor metastasis occurred." (PMID 35854294, 2022). "Besides, the apoptosis-related proteins regulated by TMED3 varied in different tumor cells." (PMID 35854294, 2022). "Also, TMED3 knockdown imposed restrictions on tumor growth in the mouse xenograft models." (PMID 35854294, 2022). "To test whether knockdown of TMED3 or SOX12 could promote full metastasis from a primary tumor to a distant organ, we subcutaneously grafted CC14 lacZ+ cells expressing pSIH lentivectors into nude mice and scored for the presence of βgal+ colonies in the lungs." (PMID 24920608, 2014). "TMED3 is significantly overexpressed in GBM, positively correlating with tumor grade and poor prognosis." (PMID 40471367, 2025). "Our results showed that TMED3 is highly expressed in GBM samples, and its overexpression correlates with higher tumor grade and poor prognosis." (PMID 40471367, 2025). "TMED3 is also heavily involved in AKT regulation; inhibiting TMED3 suppresses AKT signaling, thereby inhibiting tumor growth." (PMID 40471367, 2025). "In this study, we explored the relationship between TMED3 and GBM, including its effects on tumor proliferation, invasion, and metastasis, as well as its interaction with ZBTB7A in GBM development." (PMID 40471367, 2025). "These in vivo and in vitro experiments confirmed the role of TMED3 in promoting GBM cell proliferation and invasion, and its inhibition can suppress tumor growth." (PMID 40471367, 2025). "In summary, this study indicated that TMED3 expression was upregulated in LUSC tissues and its expression positively correlated with tumor progression." (PMID 34429402, 2021). "TMED3 up-regulation correlated with a high AFP level (P = 0.020), tumor size (P = 0.045) and vascular invasion (P < 0.001)." (PMID 27901021, 2016). "In the present study, we demonstrate that TMED3 was up-regulated in HCC tissues and was expressed at even higher levels in portal vein tumor thrombus (PVTT)." (PMID 27901021, 2016). "TMED3 participates in tumor progression, but functions of TMED3 in the brain have not been described." (PMID 37672513, 2023). "As a result, it was showed that whether the lymphatic metastasis occurred was predicted by the expression pattern of TMED3 (P = 0.038), but it was not the case regarding other patient’s/tumor’s characteristics." (PMID 35854294, 2022). "Furthermore, we examined TMED3 expression in 30 matched PVTT, primary tumor and NT tissues." (PMID 27901021, 2016). "Both TMED3 and SOX12 repress metastatic growth in the lungs, but only TMED3 also suppresses full metastasis from primary tumors, and this is not due to a simple enhancement of tumor growth." (PMID 24920608, 2014).
cancer (17 papers, 2012 to 2025). A tumor composed of atypical neoplastic, often pleomorphic cells that invade other tissues. "Based on this consideration, Duquet and collaborators show that TMED3 silencing causes a significant reduction in colon CSCs clonogenicity, thus suggesting a role for TMED3 in cancer stemness." (PMID 35805075, 2022). "Cancer-related genes such as Transmembrane emp24 domain-containing protein 3 (TMED3) have gained widespread attention due to their roles in various types of cancer." (PMID 40471367, 2025). "Emerging evidence has shown that TMED3 is closely related to cancer tumorigenesis progression, proliferation, invasion, and metastasis." (PMID 39735675, 2025). "A recent study demonstrated that TMED3 stimulates in vitro and in vivo survival and proliferation and suppresses apoptosis of chordoma cancer cells, thus serving as a positive cancer regulator." (PMID 35805075, 2022). "Through IHC assay on the tissue slides, we found that the expression of TMED3 was significantly higher in EC tissues than that in para-carcinoma tissues (P < 0.001)." (PMID 35854294, 2022). "The results in vivo demonstrated that TMED3 knockdown had an inhibitory effect on the proliferation of cancer cells, these results indicate the promotive role of TMED3 in LUSC." (PMID 34429402, 2021). "According to those results, the malignant properties of TMED2 and TMED3 in cancer are cell type-specific." (PMID 33888099, 2021). "Herein, we first evaluated the effect of TMED9 knockdown on TMED9- and TMED3-modulated signaling molecules which have been reported in other cancer types." (PMID 33888099, 2021). "The results support the potential of TPX2 in the treatment of castration-resistant tumors and highlight the induction of apoptosis due to AIM1 and TMED3 inhibition especially in the androgen independent cancer cells." (PMID 22761906, 2012). "Although the exact role of ERGIC1 and TMED3 in cancer remains to be elucidated, the dysfunction of proteostasis and ER is known to induce a stress response (unfolded protein response) leading to apoptosis in cancer cells." (PMID 22761906, 2012). "Recent research has emphasized the dual role of TMED3 in various cancers." (PMID 40471367, 2025). "The Transmembrane emp24 domain-containing protein 3 (TMED3) gene has been found to play a role in the development of various cancers, but its mechanism in GBM remains unclear." (PMID 40471367, 2025). "The clinical significance of TMED3 has been also widely investigated in other cancers." (PMID 36991473, 2023). "As far as TMED3 is concerned, its functional roles in cancers are controversial." (PMID 36991473, 2023). "Thus, several common cancer-associated elements were monitored, demonstrating that the patterns of p-AKT, CDK1, CDK6 and PIK3CA were reduced in response to TMED3 depletion." (PMID 36991473, 2023). "As far as TMED3 is concerned, its roles in cancers are controversial." (PMID 36991473, 2023). "Therefore, TMED3 is the subject of the design of potent anticancer drugs, and considered as a promising cancer therapeutic target." (PMID 34838013, 2021). "Previous studies have indicated that TMED3 may be involved in the regulation of malignant cancer behaviors." (PMID 34838013, 2021). "Transmembrane emp24 trafficking protein 3 (TMED3) may be involved in the regulation of malignant cancer behaviors." (PMID 34838013, 2021). "Additionally, we confirmed TMED3 expression in cancer tissues are higher than normal tissues by using GSE11024, GSE12606, and GSE14762)." (PMID 31057605, 2019). "TMED3 showed good predictive power in patients with low- and high-stage ccRCC, and low- and high-grade disease in the TCGA cohort and in patients with low- and high-stage cancer in the ICGC cohort." (PMID 31057605, 2019).
cancer (continued). "Analyses of transcripts altered in TMED3 kd cells over control levels revealed a group of 63 RNAs enhanced twofold or more that included several genes previously shown to promote pro-metastatic behavior in different cancers, including SOX8, ASCL2, FGF19, and CXCR4." (PMID 31253868, 2019). "Considering that controversial roles of TMED3 were reported in different cancers and little evidence was available in the context of EC, we here for the first time explored the biological role of TMED3 on EC progression." (PMID 35854294, 2022). "Especially ERGIC1 and TMED3 were found to be highly expressed in the cancer but not in the non-malignant cell lines." (PMID 22761906, 2012). "However, despite the promising results of TMED3 expression patterns in cultured prostate cells, TMED3 mRNA was expressed at equal levels in the non-malignant and cancer tissues." (PMID 22761906, 2012). "Furthermore, the gene co-expression signatures indicate that ERGIC1 and TMED3 are expressed together with genes involved in cellular redox homeostasis, in agreement to our earlier results demonstrating that ERG oncogene expressing cancer cells are sensitive to oxidative stress inducers." (PMID 22761906, 2012).
TMED3 also shares sentences with these, for which no sentence is quoted: clear cell renal cell carcinoma (3 papers); adenoma (1); glioblastoma (1); kidney cancer (1); liver cancer (1); lung carcinoma (1); metastatic prostate carcinoma (1); testis cancer (1).